HMGB1 (high mobility group box 1)
Diseases named in the same sentence as HMGB1 in open-access papers (continued):
Sharing a sentence is not in itself a finding about the gene and the disease.
tumor (continued). "We also demonstrated that HMGB1 could upregulate VEGF-C secretion in GC cell lines, suggesting that HMGB1 may enhance the invasion ability of tumor cells, at least in part, through VEGF-C-related pathways." (PMID 23866030, 2013). "In the present study, immunohistochemistry and real-time polymerase chain reaction (PCR) of HMGB1 and HMGB2 in 64 BCa patients revealed that HMGB1 and HMGB2 were overexpressed in BCa tissues compared with normal tissues, and were correlated with tumor clinical stage and pathological grade." (PMID 23426143, 2013). "Also interesting is the commonality of inflammatory pathways and tumor-signaling pathways seen in our pathway map list (Oncostatin M signaling, Epithelial-mesenchymal transition (EMT) regulation, HMGB1/RAGE, APRIL & BAFF signaling, etc.)." (PMID 24124478, 2013). "In addition, endogenous ligands for TLRs were also identified, including HSP70 and HMGB1, which have been shown to up-regulate TLR2 and TLR4 on tumor cell surfaces and induce tumor progression and metastasis." (PMID 23650534, 2013). "The ethanol-treated tumor cells expressed “eat-me” signals on the cell surface such as calreticulin (CRT) and released immunostimulatory factors such as heat shock protein (HSP)90α and high-mobility group box 1 (HMGB1)." (PMID 23717436, 2013). "HMGB1 protein might contribute to the malignant progression of HCC, high expression of HMGB1 predicts poor prognosis for patients with HCC after curative hepatectomy, especially for patients with tumor >5 cm." (PMID 22747650, 2012). "Kang and colleagues hypothesized that extracellular HMGB1, released by necrotic cells, is responsible for RAGE-mediated induction of autophagy in tumor cells." (PMID 22291707, 2012). "Subgroup analysis revealed that high expression of HMGB1 predicted poorer overall survival only for tumor >5 cm (p = 0.031), but not for tumor ≤5 cm (p = 0.101)." (PMID 22747650, 2012). "The comparison of HMGB1 expression between the tumors was not significant because all of the tumor cells exhibited the same patterns of strong nuclear expression and weak cytoplasmic expression." (PMID 22496788, 2012). "In the tumor tissues, we found that most of the tumor cells contain variable amount of cytoplasmic HMGB1, while no cytoplasmic HMGB1 was detected in normal epithelial and stromal cells." (PMID 22496788, 2012). "HMGB1 binds to several receptors, including the receptor for advanced glycation end products (RAGEs) and Toll-like receptors (TLR)-2 and TLR-4, and promotes inflammation, cell proliferation, and tumor growth and metastasis." (PMID 21917150, 2011). "Furthermore, the log-rank test was used to compare the subcellular localization of HMGB1 with the density of CD3+ and CD45RO+ cells within the tumor." (PMID 20846416, 2010). "In fact, many previous studies have demonstrated the over-expression of HMGB1 with its receptor, receptor for advanced glycation end products (RAGE), in different tumor types, including breast carcinoma, colorectal cancer, prostate cancer, pancreatic cancer, and hepatocellular carcinoma." (PMID 19476625, 2009). "Moreover, the interaction between lipid metabolism and ferroptosis may affect the release of high mobility group protein 1 (HMGB1), thereby regulating tumor immunity." (PMID 40137165, 2025). "We speculate that this may reflect a non-productive ICD phenotype, wherein tumor cells emit ICD-associated signals (e.g., calreticulin, HMGB1) but fail to initiate effective immune clearance due to a profoundly immunosuppressive microenvironment." (PMID 40909289, 2025). "Furthermore, HMGB1 is capable of activating T cells, enhancing immune surveillance, and inducing activation of NK cells and NKT cells, thereby augmenting cytotoxicity against tumor cells." (PMID 41354099, 2025).
tumor (continued). "Interestingly, they proposed that necrotic or stressed tumor cells release HMGB1 into the urinary space, where it may engage pattern-recognition receptors (e.g., RAGE, TLR4) to sustain a pro-inflammatory, tumor-promoting environment." (PMID 41009692, 2025). "These HMGB1-carrying TRAPs then directly educate B cells to become IL-10-producing immunosuppressive cells, which in turn suppress the activity of both CD4+ and CD8+ T cells, creating a potent barrier to anti-tumor immunity and fostering an environment conducive to therapy resistance." (PMID 41465435, 2025). "Immunofluorescence staining of tumor sections for HMGB1 and CRT expression revealed enhanced green fluorescence in the CFRI + L group, indicating the highest induced expression of CRT and consistent HMGB1 release, confirming the excellent effect of CFRI nanoparticles in inducing ICD effects." (PMID 40040955, 2025). "As tumor cells undergo death following BNCT treatment, they release a series of signaling molecules, such as surface-exposed calreticulin (CRT), secreted ATP, and extracellular HMGB1, which trigger adaptive immune response; this mode of cell death is known as immunogenic cell death (ICD)." (PMID 41179690, 2025). "In addition, we observed that HMGB1 and BECN1 expression increased with tumor stage." (PMID 41164196, 2025). "An oncogenic role of HMGB1—at least in specific tumor types—can therefore not be excluded." (PMID 40804938, 2025). "We provided hitherto undocumented evidence that lactate in hypoxic tumor microenvironment (TME) could initiate GFAP-dedifferentiation of SCs, and the latter enhanced dCCA progression through upregulating high mobility group box 1 (HMGB1)." (PMID 40148311, 2025). "At the mitochondrial level, oxidized HMGB1 activates NF‐κB‐p65, inducing bone marrow mesenchymal stem cells to deliver intact mitochondria to cancer cells, boosting OXPHOS capacity and ATP production to sustain self‐renewal of tumor stem cells under glucose deprivation." (PMID 41354099, 2025). "Taken together, our data strongly support the notion that HMGB1 promotes cell proliferation and autophagy in CRC cells after irradiation, indicating that the knockout of HMGB1 in combination with radiotherapy can more effectively induce autophagy in cells, resulting in the killing of tumor cells." (PMID 41164196, 2025). "HMGB1, on the other hand, activates the NF-κB pathway in Mφ via TLR4/RAGE signaling, promoting the secretion of chemokines such as CXCL9/CXCL10 and recruitment of effector T cells into the tumor microenvironment, while inhibiting Mφ polarization towards the M2 phenotype." (PMID 41019083, 2025). "However, HMGB1 enhanced by pyroptosis could further activate ERK pathway, which is a signaling participated in tumor progression through polarizing macrophage and resulting in an immunosuppressive TME." (PMID 40064873, 2025). "We observed the significant improvements were demonstrated by favorable increases of the HMGB1 and CRT levels in the tumor masses recovered from contain SK groups according to the following order, miR-497/SK-NBs > SK-NBs > free SK groups, as compared to those levels in the control tumor masses." (PMID 41583493, 2025). "HMGB1 intracellular functions can modulate GPX4 activity and lipid peroxidation, while its extracellular release dictates whether ferroptotic death culminates in immunogenic tumor clearance or in immunosuppressive escape." (PMID 41465435, 2025). "Following treatment with MMSN@Dox, both CRT expression and extracellular HMGB1 levels were significantly increased, indicating that the chemoamplifier MMSN@Dox can effectively enhance ICD, which provides a favorable prerequisite for activating anti-tumor immune responses." (PMID 40871055, 2025).
tumor (continued). "Moreover, it has been reported that the T cells activated by radiotherapy are recruited to new tumor sites by the CXCL10 secreted by tumor cells, and the release of HMGB1 facilitates the synthesis of pro‐inflammatory factors, including type I interferons, subsequently guiding CXCL10 production." (PMID 40387011, 2025). "The main DAMPs include ATP, calreticulin (CRT), high mobility group box protein B1 (HMGB1), heat shock protein (HSP), type I interferon (IFN I) and Annexin 1 (ANXA1), which then activate and recruit APCs such as macrophages and DCs to activate T cells reactive to tumor antigens." (PMID 41246345, 2025). "While the precise molecular cascade (e.g., whether HMGB1 promotes DDX3 degradation via ubiquitination) requires further investigation, our current data support a model in which HMGB1-driven DDX3 suppression releases MAPK pathway inhibition, thereby driving tumor progression." (PMID 40975711, 2025). "However, despite this well-established immunological perspective, important questions remain regarding the non-immune mechanisms through which HMGB1 contributes to tumor persistence and therapy resistance." (PMID 41465435, 2025). "The ICD in the tumor cells during PTT leads to the translocation of intracellular calreticulin (CRT) to the plasma membrane surface, accompanied by the extracellular release of heat shock protein 70 (HSP70), high-mobility group box 1 (HMGB1), and adenosine triphosphate (ATP)." (PMID 38694230, 2024). "In general, tumor cells induced by apoptosis can release DAMPs in the following order: (i) pre-apoptotic exposure of intracellular calreticulin to the cell membrane surface (ecto-CRT), (ii) early-apoptotic secretion of ATP, and (iii) post-apoptotic release of high-mobility group box 1 (HMGB1)." (PMID 39339179, 2024). "We simultaneously ectopically expressed Myc-tagged SAMD4B, Flag-tagged APOA2 and HA-tagged immune checkpoints that are mainly expressed in tumours (PD-L1, PD-L2, FGL1 or HMGB1) and demonstrated that overexpression of SAMD4B could reduce the protein level of APOA2." (PMID 38886351, 2024). "The interaction between HMGB1 and TLR4 can mediate signal transduction of the inflammatory response via MYD88, which activates the NF-κB signaling pathway, leading to the release of inflammatory factors, and ultimately triggering tumor antigen-specific T-cell immunity." (PMID 37897664, 2024). "The findings showed that CRT and HMGB1 were strongly expressed in the PEG‐CuP‐COF@ΔSt + US group, demonstrating that PEG‐CuP‐COF@ΔSt nanosystem with US irradiation could promote the immunogenicity of tumor cells." (PMID 39494618, 2024). "It has been confirmed in various OSCC cell lines (CAL-27/SCC25/SCC9) that HMGB1, upon binding to TLR4, activates the NF-κB pathway, regulates macrophage polarization by upregulating the expression of IL-10 and TGF-β, and enhances the expression of PD-L1, thus promoting tumor immune escape." (PMID 37897664, 2024). "High-mobility group box 1 (HMGB1), a nuclear non-histonic protein, is a danger signal that is exported to the cell surface from platelets for activation and regulates apoptosis and autophagy in tumor cells (TCs), depending on its redox state." (PMID 39195210, 2024). "HMGB1 triggered the infiltration of myeloid-derived suppressor cells (MDSC) in conjunction with programmed death-ligand 1 (PD-L1) upregulation, leading to immunosuppression and protecting tumor cells from the ferroptosis-induced CD8-dependent anti-tumor activity." (PMID 38540172, 2024). "HMGB1 can be actively released or passively secreted into the extracellular space in tumor cells, where it binds to the receptor RAGE on the cell membrane, acting as an alarm signal to influence a diverse processes in tumor initiation and progression by modulating downstream signaling pathways." (PMID 38529373, 2024). "Additionally, HMGB1 knockdown does not affect tumor cell proliferation but improves effector CD8+ T cell responses, causing tumor rejection." (PMID 38999957, 2024).
tumor (continued). "Hypoxic tumor cells are forced to reprogram metabolic pathways, from oxygen-dependent mitochondrial oxidative phosphorylation to oxygen-independent glycolysis, favoring the hypoxia-driven increased bioavailability of different RAGE ligands such as AGEs and HMGB1 within the TME." (PMID 38672429, 2024). "The release of high-mobility group protein B1 (HMGB1) and the secretion of multiple cytokines, including type I interferons, culminates in the maturation of the DCs and the recruitment and activation of the CD8 T cell-mediated immune response against the tumor cells." (PMID 37296876, 2023). "Furthermore, the highest CRT signals and the lowest HMGB1 signals in deep tumor areas were also detected in Pres+NIR group, indicating that remarkably stronger ICD of tumor cells was induced by Pres in the deep loosened tumor environment." (PMID 37875395, 2023). "Importantly, HMGB1 release and GSDME cleavage were observed upon the challenge of these ORFV recombinants, further confirmed the ability of these ORFV recombinants on triggering tumor cell pyroptosis." (PMID 36641456, 2023). "Compared with that in tumours, the increase of IL-1β, IL-18, and HMGB1 levels in the serum was not severe, suggesting that TIOs+NIR3-triggered antitumour immune response is relatively safe and does not cause hyperactive immune response or substantial systematic inflammation." (PMID 37673934, 2023). "In addition to promoting an innate immune response within the TIME, TLR agonists, such as the TLR-2/3 agonist, L-pampo (LP), and the TLR-7 agonist, Imiquimod, have been shown to induce tumor-cell ICD, as evidenced by enhanced ecto-CRT and the increased release of HMGB1 and ATP." (PMID 37626741, 2023). "However, as has been reported, a high level of reactive oxygen species (ROS) in the tumor microenvironment (TME) is adverse to ICD via injuring HMGB1 function 9; it is essential to consume ROS and reverse the immunosuppressive effects of the TME in order to achieve ICD of tumor cells." (PMID 37064869, 2023). "It has been found that tumor suppressor miR-410-3p and miR-29c could attenuate the resistance to GEM in PC through inhibiting expression of High mobility group box 1 (HMGB1) and ubiquitin specific peptidase-22 (USP22) and, thus, reducing autophagy, respectively." (PMID 37560164, 2023). "Previous studies have demonstrated that HMGB1 interfered with cyclin expression through a variety of downstream pathways to maintain cell growth, or through binding to surface RAGE receptors to enhance the metalloproteinases activity to promote tumor invasion and metastasis." (PMID 37518006, 2023). "In addition, it has been reported elsewhere that an OV coding for CD40L induced tumor regression in vivo by demonstrating apoptotic impacts, leading to an increased calreticulin (CRT) exposure and HMGB1 (high mobility group box 1) and ATP (adenosine triphosphate) output." (PMID 38053658, 2023). "The interaction between HMGB1 and toll-like receptor 4 induced the expression of a non-classical type I human leukocyte antigen (HLA) molecule, HLA-G, in glioma, which assists in the immune escape of the tumor." (PMID 37020242, 2023). "Furthermore, HMGB1 promotes vascular endothelial growth factor (VEGF) secretion in a RAGE-dependent manner and is also known to stimulate endothelial progenitor cells homing to tumor tissue." (PMID 37210579, 2023). "Interestingly, in some tumor areas, but independently of whether INA or IT was performed, hot spots of HMGB1 staining were observed (second-last panel)." (PMID 37894279, 2023). "HMGB1 in GBM cells is secreted to the extracellular matrix via autophagic vacuoles, and then binds to RAGE, which activates the pathway of regulating cell differentiation, growth, motility, and death and especially in promoting the proliferation and invasion of tumor cells." (PMID 37759870, 2023).
tumor (continued). "Tumor cells and platelets are able to produce microthrombi in the circulation by the binding of the platelet P-selectin to the ligands of tumor P-selectin and thanks to the interaction between platelet TLR4 and the released High Mobility Group Box 1 (HMGB1) protein from the tumor." (PMID 36901997, 2023). "MnOx‐OVA/TF NSs further induced tumor cells to release cellular debris, high mobility group protein 1 (HMGB1), and other signaling molecules after inducing ferroptosis in tumor cells, while releasing the pattern antigen OVA/TF to stimulate DCs maturation and further enhance the anti‐tumor effect." (PMID 37933288, 2023). "Consequently, it is likely that HMGB1 or the HMGB1/sRAGE ratio alone will not outperform these established tumor markers." (PMID 37894448, 2023). "The next question, which could not be done without an answer, was whether HMGB1 alone could promote the regrowth of tiny tumor cell populations." (PMID 37880798, 2023). "siRNA HMGB1 effectively downregulated HMGB1 expression in SCC-9 cells, though resulting in reduced cancer cell colony formation, as well as in increased cell apoptosis providing clear evidence on the influence of HMGB1 on the proliferation and viability of the tumor cells." (PMID 37511951, 2023). "Herein, tumor growth between HFD-fed obese and ND-fed lean mice was closely related to elevated circulating WBCs, lymphocytes, neutrophils, plasma levels of soluble P-selectin, TGF-β1 and HMGB1, as well as increased tumor expressions of HMGB1, RAGE, Smad2/3 phosphorylation, CD62P and MPO." (PMID 36012397, 2022). "We found that CD276 and VEGFA expression was significantly positively correlated with the expression of OTUD6B in nearly all types of cancer, so were the immune checkpoint inhibitor genes HMGB1 and TLR4, suggesting that OTUD6B may provide some help for tumor immunotherapy through these targets." (PMID 36052059, 2022). "Here we provide evidence that rfhSP-D treatment increased the release of HMGB1 from the nucleus and a significant translocation of CRT to the cell surface, suggesting a novel mechanism through which rfhSP-D enhances immunogenicity of the tumour via ICD induction." (PMID 35874783, 2022). "HMGB1 and its subsequent binding to RAGE can trigger the production of proinflammatory cytokines through NF-kB activation, as well as the expression of pro-invasive and proteolytic matrix metalloproteinases (MMPs), such as MMP2 and MMP9, leading to tumor invasion and metastasis." (PMID 35727208, 2022). "In particular, systemic administration of recombinant HMGB1 might not predict in which redox state the proteins will be in the vicinity of the tumor." (PMID 35887213, 2022). "However, these processes are often inhibited in tumor-infiltrating cDCs through high expression of the inhibitory receptor T-cell immunoglobulin and mucin domain 3 (TIM3), which interacts with alarmin HMGB1, inhibiting anti-tumor responses and reducing the efficacy of cancer treatments." (PMID 35784290, 2022). "To clarify this issue, we established HMGB1-knockout clones from B16F10 and CT26 tumor cells by genome editing using the clustered regularly interspaced short palindromic repeats (CRISPR)/Cas9 system, and used these clones to investigate the role of HMGB1 on the anti-tumor immunity." (PMID 35150340, 2022). "Additionally, compared to the control group, the BNCT group showed a higher human plasma HMGB1 level, measured using ELISA, on day 3, when tumor growth was significantly retarded compared to the non-irradiated control." (PMID 35336794, 2022).